LDHA (lactate dehydrogenase A)
Diseases named in the same sentence as LDHA in open-access papers (continued):
Sharing a sentence is not in itself a finding about the gene and the disease.
pancreatic cancer (continued). "LDHA is found acetylated at lysine 5 (K5) in pancreatic cancer cells, which reduces LDHA catalytic activity and decreases its protein level." (PMID 36407005, 2022). "We first assessed glycolysis-related proteins Glut1, Glut4, hexokinase I and II, PKM I and II (as well as their phosphorylated forms), PFKP, and LDHA in AdipoRon-treated pancreatic cancer cell lysates by western blot." (PMID 35121743, 2022). "It has been shown that silencing of LDHA decreases glycolysis and leads to a reactivation of mitochondrial function in breast, lung, liver, lymphoma, and pancreatic cancers (reviewed in Ref." (PMID 35877003, 2022). "In a mouse model of melanoma and pancreatic tumor with low or null LDHA, the infiltration and activation of CD8+ T cells and NK cells were enhanced, and these infiltration cells produced the increased IFN-γ and granzyme B." (PMID 36518315, 2022). "A previous study showed that FOXM1 promotes the Warburg effect and pancreatic cancer progression via transactivation of LDHA expression." (PMID 35789607, 2022). "The transcription factor Krüppel-like factor 4 (KLF4), which also binds to the promoter region of the LDHA gene, is a negative regulator of LDHA transcription in pancreatic cancer cells." (PMID 36551514, 2022). "To identify alterations that occur in pancreatic cancer cells able to survive LDHA inhibition, we treated the oxamate-sensitive glycolytic PDAC cell line MIAPaCa2 (parental cells) with 10 mM oxamate for 4 weeks to generate an oxamate-resistant PDAC cell line." (PMID 35982980, 2022). "Mechanistically, the elevated LDHA expression and enhanced L‐lactate production fuelled pancreatic cancer growth and progression, and the activity depends on the AMP‐activated protein kinase (AMPK)/ mammalian target of rapamycin (mTOR) signaling pathway." (PMID 34185423, 2021). "To further delineate the mechanism involved in LDHA‐mediated PAAD progression, we performed western‐blot analysis on LDHA‐overexpressed or ‐knockdown pancreatic cancer cells." (PMID 34185423, 2021). "The results showed that LDHA was significantly up-regulated in pancreatic cancer tissues compared with the controls, but." (PMID 34592906, 2021). "To further examine berberine's effect on LDHA expression, we performed in vitro cytotoxic assay of berberine on LDHA OE and SH pancreatic cancer cells." (PMID 34185423, 2021). "LDHA overexpression promoted colony formation in the pancreatic cancer cells, suggesting a promoted proliferation." (PMID 34185423, 2021). "It was observed that the LDHA mRNA expression was lower in the pancreatic cancer cell line with reduced invasion capability." (PMID 34185423, 2021). "On the contrary, our study in pancreatic cancer models showed that berberine inhibited LDHA expression, enzymatic activity, and lactate content in both murine serum and orthotopic tumors and prolonged survival in pancreatic cancer models." (PMID 34185423, 2021). "Our clinical and mechanistic findings indicated that LDHA overexpression leads to increased pancreatic cancer growth and metastasis, and vice versa." (PMID 34185423, 2021). "FOXM1 upregulated LDHA expression by promoting its transcription and was further attributed to pancreatic cancer cell proliferation and metastasis." (PMID 33777804, 2021). "In contrast, knocking down LDHA or PKM2 alleviated the fast growth and hypermetabolism of pancreatic cancer cells caused by inhibition of miR-489-3p." (PMID 34868902, 2021).
pancreatic cancer (continued). "To determine the effect of LDHA expression on pancreatic cancer, we first analyzed the mRNA expression and invasion capability of various pancreatic cancer cell lines." (PMID 34185423, 2021). "Observing LDHA overexpression inhibited AMPKa activation in pancreatic cancer cells, and knowing that berberine is a well‐reported AMPKa activator, we performed the molecular docking analysis on berberine and LDHA." (PMID 34185423, 2021). "In human pancreatic cancer cells, LDHA is upregulated by hypoxia and is directly activated by HIF1‐α." (PMID 32558023, 2020). "Induced expression of LDHA promotes the proliferation and migration of pancreatic cancer cells, and knocked down expression inhibits cell growth and migration." (PMID 32558023, 2020). "In addition to absorption, pancreatic cancer also shows upregulated expression of many genes encoding rate-limiting glycolytic enzymes, such as hexokinase 1/2, phosphofructokinase 1 and lactate dehydrogenase A (LDHA, the subunit of LDH), enhancing the Warburg effect and glycolytic flux to lactate." (PMID 32122374, 2020). "LDHA, a key enzyme of aerobic glycolysis and a target of c-Myc, is elevated in pancreatic cancer and promotes the tumorigenicity of pancreatic cancer cells." (PMID 32291380, 2020). "Thereupon, in this study, we detected the LC3 and LDHA in the tissue microarray and observed that stronger activity of autophagy and glycolysis were exhibited in pancreatic cancers than normal tissues." (PMID 32566037, 2020). "In human lymphoma and pancreatic cancer, knocking down the expression of LDHA by siRNA reduces ATP levels and induces significant oxidative stress and cell death in human lymphoma and pancreatic cancer xenografts in mice." (PMID 31737570, 2019). "Analysis of the LDHA expression levels in tissue sections from normal pancreas, pancreatic cystic neoplasms, as well as pancreatic intraepithelial neoplasia and pancreatic cancer, have shown LDHA is overexpressed throughout the carcinogenic process." (PMID 31035592, 2019). "FX-11, 3-dihydroxy-6-methyl-7-(phenylmethyl)-4-propylnaphthalene-1-carboxylic acid, is a selective, reversible, NADH competitive inhibitor of LDHA that has shown antitumor activity in lymphoma and pancreatic cancer xenografts." (PMID 31527446, 2019). "The targeting of glycolytic enzymes such as PKM2 and LDHA represents a promising therapeutic approach for the treatment of pancreatic cancer." (PMID 31527446, 2019). "Although most inhibitors are still in the preclinical phase, the targeting of glycolytic enzymes, such as PKM2 and LDHA, represents a very promising approach for the treatment of pancreatic cancer." (PMID 31527446, 2019). "FGFR1 directly phosphorylates the four tyrosine residues of LDHA, which promotes the stability of LDHA and increases its enzymatic activity in pancreatic cancer cells." (PMID 31035592, 2019). "Although most inhibitors are still in the preclinical phase, the targeting of glycolytic enzymes, such as PKM2 and LDHA, represents a very promising therapeutic approach for the treatment of pancreatic cancer." (PMID 31527446, 2019). "LDHA is acetylated at lysine 5 (K5) in pancreatic cancer cells, which reduces LDHA catalytic activity and decreases LDHA protein level." (PMID 31035592, 2019). "Inhibition of LDHA has been reported to impair lymphoma and pancreatic cancer growth by decreasing ATP levels, inducing oxidative stress and cell death." (PMID 31527446, 2019). "We evaluated this concept by combining the PKM2 activator, TEPP-46, with the LDHA inhibitor, FX-11, and assessed efficacy in vitro and in vivo in preclinical models of pancreatic cancer." (PMID 31527446, 2019). "In human pancreatic cancers, decreased levels of LDHA acetylation result in activation of LDHA and inhibition of LDHA degradation, eventually promotes cancer cell growth and migration." (PMID 29942010, 2018).
pancreatic cancer (continued). "Reduction of LDHA reduced ATP levels and induced significant oxidative stress and cell death in lymphoma and pancreatic cancer cells." (PMID 28915924, 2017). "The key role of LDHA in maintaining the Warburg phenotype in cancer cells was confirmed by several reports of LDHA inhibition or knockdown severely diminishing tumorigenicity in breast, lung, liver, lymphoma, and pancreas cancers." (PMID 29326883, 2017). "Inhibition of LDH-A enzyme activity and the consequent decrease in LDH-A protein level was shown to reduce K5 acetylation of lactate dehydrogenase A (LDH-A) in a study on human pancreatic cancers." (PMID 29179522, 2017). "Our results concur with their findings showing significant overexpression of PKM2 and LDHA in pancreatic cancers compared with normal pancreatic tissue." (PMID 26989901, 2016). "LDHA is reported to be upregulated in many cancers, including gastric cancer, renal cell carcinoma, pancreatic cancer, esophageal squamous cell carcinoma and others." (PMID 26902416, 2016). "Our results demonstrate that both PKM2 or LDHA are significant prognostic markers in pancreatic cancer and the combination provides improved stratification of outcome." (PMID 26989901, 2016). "Overexpression of PKM2 or LDHA has been reported in the tissues of a number of cancers, including cholangiocarcinoma, colorectal cancer, non-small cell lung cancer and pancreatic cancer." (PMID 26989901, 2016). "PKM2 and LDHA expression was also assessed by Western blot in 10 human pancreatic cancer cell lines." (PMID 26989901, 2016). "A previous report showed that FOXM1 played important roles in reprogramming of glucose metabolism in pancreatic cancer via transcriptional regulation of LDHA expression." (PMID 27351131, 2016). "Graviola treatment also affected the expression of molecules related to hypoxia and glycolysis (HIF-1α, NF-κB, GLUT1, GLUT4, hexokinase II and lactate dehydrogenase-A) in pancreatic cancer cells." (PMID 26979487, 2016). "Recently, FOXM1 was found to regulate glucose metabolism in pancreatic cancer via transactivation of LDHA expression." (PMID 27351131, 2016). "By Western blotting, high expression of PKM2 and LDHA was detected in 8 and 9 out of the 10 pancreatic cancer cell lines." (PMID 26989901, 2016). "Depletion of LDHA levels in human pancreatic cancer cells also influence aerobic glycolysis in, led to decreased lactate production and glucose uptake, and decreased in intracellular ATP levels." (PMID 26062441, 2015). "LDHA has been shown correlation with clinicopathologic features and survival of patients with pancreatic cancer, renal cell carcinoma, esophageal squamous, and gastric cancer." (PMID 26062441, 2015). "Numerous studies had shown that LDHA is overexpressed in pancreatic cancer and regulates aerobic glycolysis of pancreatic cancer." (PMID 26062441, 2015). "Knocking down the expression of LDHA in human hepatocellular carcinoma cells and pancreatic cancer cells inhibited cell growth dramatically by activation of the apoptosis pathway." (PMID 26017754, 2015). "To explore and confirm the role of LDHA in cancer cells, we deleted the expression of LDHA in colorectal cancer and pancreatic cancer cell lines by shRNA." (PMID 26062441, 2015). "We confirmed that the expression levels of LDHA were significantly higher in pancreatic cancer tissues (tumor) compared to their matched adjacent normal tissues (normal)." (PMID 26062441, 2015). "We also observed that there is a decreased cell proliferation in pancreatic cancer cells after deletion of LDHA." (PMID 26062441, 2015). "The expressions of GLUT1 and LDHA were inhibited remarkably after Pfn1 upregulation, thereby contributing to glycolytic pathways that are crucial for pancreatic cancer progression." (PMID 25103363, 2014). "We observed a reduced expression of glucose transporter GLUT1 and glycolytic enzyme LDHA in pancreatic cancer cells upon treatment with ketone bodies." (PMID 25228990, 2014).
pancreatic cancer (continued). "Accordingly, inhibition of expression of the gene encoding lactate dehydrogenase A (LDHA) by siRNA or LDHA inhibition by a small-molecule inhibitor induces significant cell death and inhibits progression of human lymphoma and pancreatic cancer xenografts." (PMID 22988443, 2012). "They identified an LDHA–H4K12la–immune-gene axis that links glycolytic metabolism, epigenetic regulation and immune signaling, highlighting this pathway as a potential target for therapeutic intervention in pancreatic cancer." (PMID 41458606, 2025). "Therefore, among the cancer types with elevated LDHA activity and a hypoxic microenvironment, pancreatic cancer was once again prevalent." (PMID 40091035, 2025). "Moreover, KRAS G12D extinction also downregulates several rate-limiting glycolytic enzymes like HK1, hexokinase 2 (HK2), PFKl and lactate dehydrogenase A (LDHA), while decreasing the glucose uptake and lactate production in pancreatic cancer." (PMID 39806421, 2025). "The study of Ge W. showed, though, that NK cell’s functional impairment might be directly associated with lactate via sine oculis homeobox homolog 1 (SIX1)/lactate dehydrogenase A (LDHA) axis in pancreatic cancer." (PMID 40361394, 2025). "Indeed, the HIF‐1α‐induced activation of LDHA and its facilitation of lactate production have been reported in various diseases, such as pancreatic cancer, supporting the findings of our study." (PMID 40176272, 2025). "Notably, ZDHHC9-mediated LDHA palmitoylation is upregulated in gemcitabine-resistant pancreatic cancer." (PMID 40977744, 2025). "Our findings suggest that targeting the FOXO3a/miR-4259/LDHA pathway may serve as a new treatment for pancreatic cancer, especially in patients with a poor response to gemcitabine chemotherapy." (PMID 39930542, 2025). "These clinical observations suggest that the expression of FOXO3a and miR-4259 positively correlates with recurrence-free survival outcomes in pancreatic cancer patients treated with gemcitabine and inversely correlates with the expression of LDHA and CSC markers within this cohort." (PMID 39930542, 2025). "To investigate regulators involved in LDHA-mediated gemcitabine resistance and CSC of pancreatic cancer cells, we further used a combination of the miRNA microarray results and software predictions and confirmed that miR-4259 is a direct target of LDHA by luciferase assay." (PMID 39930542, 2025). "Moreover, we analyze the LDHA expression correlates with pancreatic cancer patients’ survival rates by PROGgeneV2 online database and found that high expression levels of LDHA have lower overall survival and relapse-free survival in pancreatic cancer patients." (PMID 39930542, 2025). "Many human cancer cell lines, such as those from pediatric osteosarcoma, lymphoma, prostate cancer, gallbladder carcinoma, hepatocellular carcinoma, or pancreatic cancer, have been shown to exhibit abnormal overexpression of LDHA, which can also promote cancer proliferation, migration, and invasion." (PMID 40091035, 2025). "In various digestive tumors, including gastric, esophageal, colorectal, and pancreatic cancers, the high expression of lactate dehydrogenase A (LDHA)—a key enzyme in the aerobic glycolysis pathway of tumor cells—is often associated with poor prognosis and a high metastatic rate." (PMID 39596288, 2024). "Previous studies have found LDHA could promote the progression of lung cancer, lung adenocarcinoma, pancreatic cancer, and renal clear cell carcinoma." (PMID 38919521, 2024). "In addition, deacetylation of LDHA by SIRT2 deacetylase increases LDHA activity in pancreatic cancer." (PMID 39468303, 2024). "Analysis of the public PDAC scRNA-seq data also revealed that primary pancreatic tumors of PDAC patients with high LDHA expression levels showed decreased proportions of CD8+ T cells and DCs among CD45+ cells compared with normal pancreatic tissues of individuals without PDAC." (PMID 39343933, 2024).
pancreatic cancer (continued). "Furthermore, we illustrated that the downregulation of LDHA in pancreatic cancer heightened the antitumor immune response of CD8+ T cells and enhanced the antitumoral polarization of macrophages." (PMID 38664705, 2024). "In addition, another study reported that LDHA knockdown in Pan02 cells (a pancreatic cancer cell line) substantially repressed the tumorigenicity of these cells in mice." (PMID 38627278, 2024). "Combined with our in vitro results obtained with the pancreatic cancer cell line PANC-1, these results suggest that lactate incorporation into histones through nuclear LDHA may have implications for pancreatic cancer tumorigenesis." (PMID 37779146, 2023). "Besides, high expression of LDHA is correlated with tumor differentiation of pancreatic cancer, which can enhance aerobic glycolysis, resulting in cancer cell proliferation and growth." (PMID 37333498, 2023). "Also, FOXM1 plays crucial functions in aerobic glycolysis in pancreatic cancer via transcriptional regulating LDHA function." (PMID 37159818, 2023). "Almost ten years ago, aberrant activation of the KRAS pathway was shown to promote glucose avidity in pancreatic tumors, whereby KRAS mutations were associated with the upregulation of the glucose transporter GLUT1, and enzymes that execute aerobic glycolysis, such as LDHA." (PMID 37408249, 2023). "Moreover, berberine has shown the ability to suppress LDHA activity, inhibiting pancreatic cancer cell proliferation." (PMID 37915411, 2023). "In addition, acetylation of lysine 5 on LDHA has been reported to reduce its activity in pancreatic cancer." (PMID 35525866, 2022). "In pancreatic cancer, over-expressed ubiquitin carboxyl-terminal hydrolase L3 (UCHL3) was reported to stabilize Forkhead box protein M1 (FOXM1), which activates the transcription of LDHA, and promotes aerobic glycolysis of pancreatic cancer through the UCHL3-FOXM1-LDHA axis." (PMID 35307036, 2022). "Interestingly, there is a point mutation in the 3′-UTR of LDHA (rs18407893 at 11p15.4) in HCT116 colon and BxPC3 pancreatic cancer cells as well as four of 30 samples Aspire of colorectal cancer tissues." (PMID 36518315, 2022). "Survival in pancreatic cancer can indeed be predicted by the glucose metabolism key gene LDHA." (PMID 35755820, 2022). "Furthermore, the qPCR results indicated the mRNA expression levels of JMJD6, ANKZF1, CITED2, and ENO3 was obviously decreased in pancreatic cancer cells versus the normal pancreatic ductal epithelial cells, whereas those of LDHA, TES, and SIAH2 were oppisite." (PMID 35935823, 2022). "In addition, FX11, an inhibitor of LDHA, has been determined to have preclinical efficiency in prostate cancer, osteosarcoma, pancreatic cancer, and lymphoma." (PMID 33795650, 2021). "This may be the potential mechanism by which pancreatic cancer shows different responses to LDHA inhibitors." (PMID 33795650, 2021). "Interestingly, FOXM1 (B) has been demonstrated to promote the Warburg effect in pancreatic cancer by increasing LDHA transcription." (PMID 33314660, 2021). "Our previous results demonstrated that miR-489-3p could regulate the progression of pancreatic cancer and target LDHA and PKM2." (PMID 34868902, 2021). "It was observed that berberine potently suppressed LDHA‐OE pancreatic cancer cell growth." (PMID 34185423, 2021). "Our research demonstrated that aberrant expression of miR-489-3p could modulate the progression of pancreatic cancer via targeting LDHA and PKM2." (PMID 34868902, 2021). "LDHA, which catalyzes the last step of glycolysis, is upregulated in pancreatic cancer specimens." (PMID 31861288, 2019). "Thus, in many types of spontaneous cancers (e.g., pancreatic cancer, prostate cancer, gliomas and cutaneous melanoma metastases), an elevated LDHA expression is observed compared to normal tissues." (PMID 31035592, 2019). "Moreover, inhibition of LDHA in combination with gemcitabine has shown synergistic cytotoxic activity in pancreatic cancer cells." (PMID 31527446, 2019).